CENPM (centromere protein M)
Description:
Component of the CENPA-NAC (nucleosome-associated) complex, a complex that plays a central role in assembly of kinetochore proteins, mitotic progression and chromosome segregation. The CENPA-NAC complex recruits the CENPA-CAD (nucleosome distal) complex and may be involved in incorporation of newly synthesized CENPA into centromeres.
Synonyms: CENP-M; C22orf18; PANE1; MGC861
Tractability: PROTAC: ubiquitination databases record sites on it.
Gene: Protein-coding gene on chromosome 22 (41,927,514 to 41,947,183, reverse strand). Ensembl gene ENSG00000100162.
Subcellular location: Nucleus; Cytoplasm; Chromosome, centromere, kinetochore
Pathways (Reactome):
Cell Cycle: Amplification of signal from unattached kinetochores via a MAD2 inhibitory signal; Deposition of new CENPA-containing nucleosomes at the centromere; EML4 and NUDC in mitotic spindle formation; Mitotic Prometaphase; Resolution of Sister Chromatid Cohesion; Separation of Sister Chromatids
Signal Transduction: RHO GTPases Activate Formins
Gene Ontology:
Biological process: chromosome segregation
Cellular component: inner kinetochore; cytosol; nucleoplasm; nucleus; cytoplasm
Genetic constraint (gnomAD): Loss-of-function variants: 14 observed, 21.09 expected, observed/expected ratio (o/e) 0.66, 90% interval 0.44 to 1.04. The upper end of that interval is the gene's LOEUF score, 1.04, which puts it in group 4 of 6, group 1 being the genes least tolerant of losing a copy. Missense variants: 239 observed, 241.79 expected, observed/expected ratio (o/e) 0.99, 90% interval 0.89 to 1.1. Synonymous variants: 114 observed, 108.84 expected, observed/expected ratio (o/e) 1.05, 90% interval 0.9 to 1.22.
Homologues: Orthologues: chimpanzee CENPM (100% identical), macaque CENPM (99% identical), dog CENPM (87% identical), guinea pig CENPM (82% identical), mouse Cenpm (79% identical), rat Cenpm (74% identical), pig CENPM (72% identical), tropical clawed frog cenpm (49% identical), zebrafish pane1 (42% identical).
Diseases named in the same sentence as CENPM in open-access papers:
CENPM is named in the same sentence as 25 diseases in open-access papers, as found by Europe PMC text mining. Sharing a sentence is not in itself a finding about the gene and the disease. The quoted sentences say what the papers report.
hepatocellular carcinoma (9 papers, 2019 to 2025). A malignant tumor that arises from hepatocytes. "CENPM is upregulated in several cancers such as melanoma, hepatocellular carcinoma, pancreatic cancer, lung adenocarcinoma, and ovarian cancer." (PMID 39778025, 2025). "LINC00882 is upregulated by activating transcription factor (ATF) in hepatocellular carcinoma and promotes tumor progression by abolishing miR-214-3p-mediated degradation of centromere protein M mRNA." (PMID 35030969, 2022). "In this work, we performed a detailed assessment of CENPM expression in hepatocellular carcinoma based on the TCGA database and explored its relationship with clinicopathological features, survival, function, immune infiltration, and expression differences." (PMID 32863765, 2020). "To date, this study demonstrates for the first time the important role of CENPM in the prognosis of hepatocellular carcinoma." (PMID 32863765, 2020). "Our study for the first time investigated the CENPM mRNA expression and its prognostic significance in hepatocellular carcinoma." (PMID 32863765, 2020). "In our study, we evaluated the expression of CENPM in hepatocellular carcinoma based on data obtained from an online database." (PMID 32863765, 2020). "Multivariate analysis showed that the expression of CENPM and M classification was an independent prognostic factor for patients with hepatocellular carcinoma." (PMID 32863765, 2020). "Then we explored the mechanisms of CENPM-mediated regulations on hepatoma cells and detected that depletion of CENPM dramatically suppressed cellular proliferation, cell invasion and cell migratory capacity." (PMID 31703591, 2019). "HCG18 can contribute to hepatocellular carcinoma progression by increasing CENPM expression." (PMID 34976998, 2021). "However, future clinical trials are needed to validate these results and promote the use of CENPM in the prognostic evaluation of hepatocellular carcinoma." (PMID 32863765, 2020). "Finally, we also found that miR-1270 was a negative regulator and participated in post-transcriptional regulation of CENPM, and hepatitis B virus X protein (HBx) can promote hepatocellular carcinoma by suppressing miR1270." (PMID 31703591, 2019). "The CENPM expression was higher in hepatoma cells than in the immortalized liver cell line L02." (PMID 31703591, 2019). "The univariate and multivariate analysis also suggested CENPM still remained freely connected with OS and recommended that CENPM may act as a potential prognostic biomarker of prognosis and therapeutic target in hepatocellular carcinoma, but more researches needed to conduct for further study." (PMID 32863765, 2020).
liver cancer (6 papers, 2019 to 2024). An epithelial or non-epithelial malignant neoplasm that arises from the liver. "The expression of CENPM is up-regulated in liver cancer, with poor prognosis and silencing CENPM suppresses cell proliferation, migration, and invasion, while depletion of CENPM can promote apoptosis and stagnant cell cycle." (PMID 38693472, 2024). "Other study has demonstrated that lncRNA HCG18 promotes the proliferation and migration of liver cancer by hsa-miR-214-3p to regulate the expression of CENPM protein." (PMID 35590240, 2022). "The correlation between CENPM in liver cancer expression and the abundance of immune infiltrates was statistically significant (P < 0.01)." (PMID 32863765, 2020). "In order to determine the biological interaction network of CENPM in liver cancer, we used the network in the "Network" tab in cBioPortal, showing the 50 most frequently changed neighbor genes in CENPM, and the most common change was RAD21 (18.3%)." (PMID 32863765, 2020). "In the age subgroup (normal age (21–40 years), normal age (41–60 years), normal age (61–80 years) and normal age (81–100 years)), among patients with liver cancer CENPM has substantially higher transcription levels than healthy individuals." (PMID 32863765, 2020). "Centromere protein M (CENPM) has been proved to be over-expressed in HCC tissues, but carcinogenic mechanism of CENPM contributing to liver cancer is poorly understood." (PMID 31703591, 2019). "To identify useful pathways that may be differentially initiated in liver cancer, we performed a GSEA analysis between low and high CENPM expression datasets." (PMID 32863765, 2020).
bladder cancer (4 papers, 2019 to 2021). "CENMP was identified as a key candidate gene involved in melanoma metastasis, and low expression of CENPM correlated with better progression-free survival in bladder cancer than high expression." (PMID 33591950, 2021). "Low-expression of CENPM was related to a better overall survival rate in bladder cancer." (PMID 31703591, 2019).
breast carcinoma (3 papers, 2022 to 2024). "Our study, utilizing bioinformatics and breast cancer samples acquired at our institution, has validated that the overexpression of CENPM is linked to an unfavorable prognosis in breast cancer." (PMID 38200449, 2024). "The oncogene CENPM is associated with breast cancer and is involved in cell proliferation and immune infiltration." (PMID 38200449, 2024). "Research findings indicate that elevated levels of CENPM are linked to patient outcomes in breast cancer and various clinicopathological features." (PMID 38200449, 2024). "The results indicate that an elevated expression of CENPM is associated with the pro-tumor immune condition of breast cancer." (PMID 38200449, 2024). "In summary, our study findings indicate that CENPM may serve as a cancer-causing gene in breast cancer and also as a biomarker for predicting the efficacy of immunotherapy." (PMID 38200449, 2024). "Nevertheless, further investigation is required to ascertain the mechanism behind the involvement of CENPM in the progression of breast cancer." (PMID 38200449, 2024). "We conducted an enrichment analysis of CENPM using the clusterProfiler R software tool, utilizing data obtained from breast cancer patients and specimens at our institution." (PMID 38200449, 2024). "The impact of CENPM on the growth of breast cancer cells was evaluated through the utilization of the CCK8 test and the colony formation assay." (PMID 38200449, 2024). "In order to validate the impact of CENPM on malignant characteristics of breast cancer, such as proliferation and migration, the CCK8 proliferation assay and the colony formation assay were employed." (PMID 38200449, 2024). "Based on our analysis, the excessive expression of CENPM results in the infiltration of immune cells that promote tumor growth in breast cancer, while suppressing the infiltration of anti-tumor cells such as CTL and Mast cells." (PMID 38200449, 2024). "A correlation was observed between elevated CENPM levels in breast cancer patients and a worse prognosis." (PMID 38200449, 2024). "By conducting this analysis, we were able to explore the possibility of utilizing CENPM for the clinical management of breast cancer." (PMID 38200449, 2024). "At our center, we confirmed the overexpression of CENPM in breast cancer samples both at the transcriptional level and the translational level." (PMID 38200449, 2024). "Using data from the TCGA, we examined the correlation between the expression of CENPM, the prognosis, and the clinicopathological features of individuals diagnosed with breast cancer." (PMID 38200449, 2024). "The effect of CENPM on the migration of breast cancer cells was assessed using scratch and transwell assays." (PMID 38200449, 2024). "In our study, we also investigated the impact of CENPM expression on the molecular pathways of breast cancer." (PMID 38200449, 2024). "Our findings indicate that CENPM may function as an oncogene in breast cancer, as well as a new target for immune checkpoint inhibitors." (PMID 38200449, 2024). "The involvement of centromere protein M (CENPM) in various types of cancer has been established, however, its impact on breast cancer and immune infiltration remains unknown." (PMID 38200449, 2024). "In addition to examining the correlation between CENPM expression and genes associated with immune checkpoints, the TIDE algorithm was employed to explore the potential of CENPM as a biomarker for immunotherapy in breast cancer." (PMID 38200449, 2024). "This factor may contribute to the deterioration of prognosis and the advancement of breast cancer in cases of CENPM." (PMID 38200449, 2024). "Elevating the expression of CENPM in breast cancer could potentially lead to the overactivation of various oncogenic pathways, particularly those involved in regulating cell proliferation." (PMID 38200449, 2024).
breast carcinoma (continued). "Additionally, the coexpression of CENPM with the majority of genes related to immune checkpoints indicates its potential to forecast the effectiveness of treatment in breast cancer." (PMID 38200449, 2024). "The results of our study suggest that CENPM could potentially function as a gene responsible for breast cancer development, in addition to serving as a promising biomarker for treatment effectiveness and a novel target for immunotherapy in breast cancer." (PMID 38200449, 2024). "Nevertheless, the connection between CENPM and breast cancer remains unclear." (PMID 38200449, 2024).
lung adenocarcinoma (3 papers, 2022 to 2025). A carcinoma that arises from the lung and is characterized by the presence of malignant glandular epithelial cells. "Upregulation of CENPM promotes hepatocarcinogenesis and facilitates tumour metastasis of melanoma, pancreatic cancer, and lung adenocarcinoma." (PMID 39778025, 2025). "CENPM is up-regulated in lung adenocarcinoma, which can promote lung adenocarcinoma cell cycle, cell proliferation, migration, and invasion, while inhibiting apoptosis." (PMID 38693472, 2024). "Finally, a comprehensive analysis of TCGA, GEPIA and Kaplan-Meier Plotter databases revealed that high mRNA expression of CCNB1, CDC25C, CENPM, and EXO1 was associated with poor survival in lung adenocarcinoma patients." (PMID 35646074, 2022).
pancreatic cancer (3 papers, 2023 to 2025). "In pancreatic cancer, CENPM is overexpressed, and down-regulation of CENPM inhibits pancreatic cancer cell proliferation, alters cell cycle, and restricts migration, and invasion." (PMID 38693472, 2024). "CENPM, a component of the CENPA-nucleosome associated complex, has also been reported to be associated with liver and pancreatic cancers." (PMID 36635779, 2023).
prostate carcinoma (2 papers, 2022 to 2024). A carcinoma that arises from epithelial cells of the prostate gland. "In a group of individuals diagnosed with prostate cancer, the correlation between CENPM expression and patient prognosis was assessed by examining its association with OS, RFS, and DMFS." (PMID 38200449, 2024).
adrenocortical adenoma (1 paper, 2025). "The immunohistochemistry results revealed that the protein level of CENPM was enhanced in ACC patients than in normal adrenal gland tissues and adrenocortical adenoma patients." (PMID 39778025, 2025).
breast ductal carcinoma (1 paper, 2021). "In the Richardson dataset, the CCDC167 gene and its co-expressed genes, such as SAC3D1, SPC24, CENPM and DEPDC1B, were substantially upregulated in breast ductal carcinoma compared to the normal group." (PMID 33461170, 2021).
breast invasive carcinoma (1 paper, 2024). "In the TCGA-GTEx-BRCA database, ROC curves were generated to assess the accuracy of diagnosing breast invasive carcinoma using CENPM expression levels (AUC = 0.953, CI 0.936–0.971)." (PMID 38200449, 2024).
breast tumor (1 paper, 2024). "Suppression of CENPM hampers the growth and movement of breast tumor cells." (PMID 38200449, 2024).
glioma (1 paper, 2019). A benign or malignant brain and spinal cord tumor that arises from glial cells (astrocytes, oligodendrocytes, ependymal cells). "The identified DryNB included seven genes (KIF2C, CCNA2, NDC80, KIF11, KIF23, ANLN and CENPM) that were significantly associated with drug sensitivity or resistance of glioma patients to the targeted therapies." (PMID 31682596, 2019). "The clinical data verified the association of the identified genes (i.e., KIF2C, CCNA2, NDC80, KIF11, KIF23, ANLN, and CENPM) with the targeted therapy response and prognosis of glioma patients." (PMID 31682596, 2019).
renal carcinoma (1 paper, 2023). A carcinoma arising from the epithelium of the renal parenchyma or the renal pelvis. "Here, therefore, we first validated the upregulation of CENPM through other public datasets and renal cancer cell lines, and then analysed the association of its expression with the prognosis of ccRCC patients." (PMID 36635779, 2023). "CENPM was significantly upregulated in ccRCC tissues and renal cancer cell lines and was closely associated with poor clinicopathological features and prognosis." (PMID 36635779, 2023). "Quantitative polymerase chain reaction (qPCR) analysis was performed to validate the expression of CENPM in renal cancer cell lines." (PMID 36635779, 2023). "Similarly, the up-regulation of CENPM was further confirmed in three renal cancer cell lines." (PMID 36635779, 2023).
triple-negative breast carcinoma (1 paper, 2024). An invasive breast carcinoma which is negative for expression of estrogen receptor (ER), progesterone receptor (PR), and human epidermal growth factor receptor 2 (HER2). "A higher T-stage was associated with the overexpression of CENPM in contrast to the N-stage, and triple-negative breast cancer exhibited greater CENPM expression when compared to hormone receptor-positive breast cancer." (PMID 38200449, 2024).
cancer (15 papers, 2016 to 2025). A tumor composed of atypical neoplastic, often pleomorphic cells that invade other tissues. "Furthermore, the upregulation of CENPM in human cancer tissues has been found to be associated with certain malignant phenotypes." (PMID 36635779, 2023). "Representative Cyclin D1 target genes were chromosome segregation factors such as AURKB and CENPM that have previously been identified as targets of Cyclin D1 in mouse embryonic fibroblasts and have been implicated in chromosome instability in cancers." (PMID 26883361, 2016). "Data from RNA‐seq and microarray were analyzed to reveal correlations of the CENPM gene with cancer, metastasis, and survival in ACC." (PMID 39778025, 2025). "In this study, the analysis of TCGA data was conducted to investigate the expression of CENPM in various types of cancers and its correlation with patient prognosis." (PMID 38200449, 2024). "We examined the expression of CENPM in different cancer types by utilizing the Cancer Genome Atlas (TCGA) and Genotype Tissue Expression Pan-Cancer (GEO) databases." (PMID 38200449, 2024). "Previous evidence indicates that upregulation of CENPM promotes cancer progression through the mTOR signaling pathway." (PMID 39325536, 2024). "CENPM and SUSD2 have roles in cell cycling and proliferation with mutations associated with cancers." (PMID 36952446, 2023). "In view of the cancer-promoting role of CENPM in a variety of human cancers, we performed a pan-cancer analysis of CENPM at the mRNA level through the TCGA database." (PMID 36635779, 2023). "Based on TCGA datasets, we observed CENPM displayed a high level in most types of cancers, and CENPM levels were distinctly upregulated in HCC specimens, especially in those with advanced stages." (PMID 34513693, 2021). "The levels of CENPM were observed to appear preferentially in immunity cells involving cancer specimens and cancer derived cells." (PMID 34513693, 2021). "In our research, we showed CENPM was over-expressed in HCC specimens compared to the corresponding para-carcinoma tissues, which was in accordance with bioinformatics, and CENPM was also discovered to be up-regulated in six HCC cell lines." (PMID 31703591, 2019). "Clearly, this also supports the link between CENPM and cancer aggressiveness to a certain extent." (PMID 36635779, 2023). "The results showed that CENPM was overexpressed in various cancers (P < 0.05)." (PMID 32863765, 2020). "In our findings, the significant expression of CENPM suggests that CENPM may play an important role in regulating cancer progression." (PMID 32863765, 2020). "CENPM may influence cell cycle, DNA replication, RNA degradation then controls the begins and development of cancer cells." (PMID 32863765, 2020). "If CENPM overexpression is the mainspring of tumor progression, inhibition of its expression level in cancer cells might stop tumor proliferation." (PMID 31703591, 2019). "CENPM may act as a potential target of chemotherapeutics whose main role is preventing tubulin formation or promoting decomposition to inhibit cell mitosis, thereby enhancing the chemotherapeutic sensitivity of cancers." (PMID 31703591, 2019). "By analysing the TCGA database, we found that CCNB1, CDC25C, CENPM, and EXO1 were highly expressed in almost all of the 33 cancers, and we also noticed significant high expression in LUAD." (PMID 35646074, 2022).